GRB2 (growth factor receptor bound protein 2)
Diseases named in the same sentence as GRB2 in open-access papers (continued):
Sharing a sentence is not in itself a finding about the gene and the disease.
tumor (continued). "Our correlation analysis in HCC tumor tissues revealed a significant negative correlation between the protein expression levels of RNF173 and GRB2." (PMID 37626338, 2023). "A small network of downregulated genes was found in tumor cells, in which EGF and beta-c interact with Shc and a complex comprising EGF, ErbB1, Shc-1, Grb2, and Sos (not shown)." (PMID 21464922, 2011). "When adjusted for gender, age, and tumor size, the prognostic effects of KPNA2 (p < 0.001) and NRAS (p < 0.05) also existed, whereas the independent prognostic value of GRB2 was not so significant (p = 0.074, p > 0.05)." (PMID 33193737, 2020). "The phosphopeptide binding assay was performed on 4 different cell types derived from the non-tumorigenic epithelium (MCF10A) and ER positive tumor cells (MCF7, T47D) and a breast metastatic (MDA-MB231) cell line to detect and compare the GRB2-phosphoprotein interactome networks." (PMID 23826330, 2013).
infection (6 papers, 2013 to 2024). The state of being infected such as from the introduction of a foreign agent such as serum, vaccine, antigenic substance or organism. "While GRB2 suppression solely would have indicated a regulatory immune response to infection in these settings, the observed GRM2 indicates a more multidimensional effector function of T cells." (PMID 38433833, 2024). "(A) Representative images showing the recruitment of Nck, WIP, Grb2, and N-WASP to actin tails in HeLa cells infected with a recombinant virus expressing the p14 N-G construct at the A36 locus at 8 hr post-infection." (PMID 35796545, 2022). "Binding of Grb2 and c-Cbl by EGFR is essential for infection." (PMID 23633955, 2013). "Finally, recruitment of the adaptor proteins Grb2 and c-Cbl by EGFR is essential for infection by C. pneumoniae." (PMID 23633955, 2013).
neurodegenerative disease (2 papers, 2017 to 2020). A disorder of the central nervous system characterized by gradual and progressive loss of neural tissue and neurologic function. "Our group first demonstrated in HD, another progressive neurodegenerative disease, that elevated expression of Grb2 in HD animal and cell models reduces aggregation of mutant Huntingtin (Htt) protein, the hallmark of HD." (PMID 28360125, 2017).
metabolic disorders (1 paper, 2019). "The data suggest that aging subjects develop cardiac abnormalities due to metabolic disorders in numerous metabolites as well as alterations in gene expressions, such as SOS1, CREB, IRS1, GRB2 and GSK3β." (PMID 30669571, 2019).
neurodevelopmental disorder (1 paper, 2022). A behavioral and cognitive disorder with onset during the developmental period that involves impaired or aberrant development of intellectual, motor, or social functions. "Although many kinesins have been associated with neurodevelopmental disorders, KIF26A is unique because it does not function as a molecular motor, but instead modulates signal transduction via direct binding to FAK and GRB2." (PMID 36228617, 2022).
GRB2 also shares sentences with these, for which no sentence is quoted: thyroid cancer (4 papers); cholangiocarcinoma (3); Parkinson disease (3); breast (2); colon adenocarcinoma (2); hepatitis B (2); liver disease (2); lymph node metastasis (2); multiple myeloma (2); myelodysplastic syndrome (2); myopia (2); T-LGL leukemia (2); acute lymphoblastic leukemia (1); adenocarcinoma (1); alcohol abuse (1); amyloid (1); ankylosing spondylitis (1); anorexia nervosa (1); autism spectrum disorder (1); B cell lymphoma (1); bulimia nervosa (1); cardiovascular diseases (1); cervical squamous cell carcinoma (1); cervical tumors (1); Cirrhosis (1); cognitive disorder (1); cyst (1); Diabetic Nephropathy (1); diabetic neuropathy (1); dilated cardiomyopathy (1).
A further 41 diseases each share a sentence with GRB2 in 1 paper.